ENDOD1 (endonuclease domain containing 1)
Description:
May act as a DNase and a RNase. Plays a role in the modulation of innate immune signaling through the cGAS-STING pathway by interacting with RNF26.
Synonyms: KIAA0830
Tractability: Antibody: UniProt places it where antibodies can reach, with high confidence; its Gene Ontology location is reachable by antibodies, with high confidence; UniProt predicts a signal peptide or a membrane-spanning region. PROTAC: ubiquitination databases record sites on it; its protein half-life has been measured.
Target class: Enzyme; Hydrolase
Gene: Protein-coding gene on chromosome 11 (95,089,817 to 95,132,645, forward strand). Ensembl gene ENSG00000149218.
Subcellular location: Secreted
Subcellular location (Human Protein Atlas): Nuclear membrane; Predicted to be secreted
Pathways (Reactome):
Hemostasis: Platelet degranulation
Gene Ontology:
Molecular function: protein binding; hydrolase activity; metal ion binding; nucleic acid binding
Cellular component: extracellular exosome; membrane; cytosol; extracellular region; nucleus
Genetic constraint (gnomAD): Loss-of-function variants: 12 observed, 9.62 expected, observed/expected ratio (o/e) 1.25, 90% interval 0.79 to 1.84. That is too few expected variants to judge how well the gene tolerates losing a copy. Missense variants: 648 observed, 616.64 expected, observed/expected ratio (o/e) 1.05, 90% interval 0.98 to 1.12. Synonymous variants: 255 observed, 243.05 expected, observed/expected ratio (o/e) 1.05, 90% interval 0.95 to 1.16.
Homologues: Orthologues: chimpanzee ENDOD1 (99% identical), macaque ENDOD1 (97% identical), pig ENDOD1 (78% identical), dog ENDOD1 (77% identical), mouse Endod1 (76% identical), rat Endod1 (76% identical), guinea pig ENDOD1 (74% identical), rabbit ENDOD1 (71% identical), tropical clawed frog endod1 (37% identical), zebrafish si:ch211-165i18.2 (23% identical), zebrafish zgc:171534 (9% identical).
Diseases named in the same sentence as ENDOD1 in open-access papers:
ENDOD1 is named in the same sentence as 16 diseases in open-access papers, as found by Europe PMC text mining. Sharing a sentence is not in itself a finding about the gene and the disease. The quoted sentences say what the papers report.
prostate carcinoma (5 papers, 2011 to 2025). A carcinoma that arises from epithelial cells of the prostate gland. "The final protein identified with altered expression in the contralateral cortex was endonuclease domain-containing 1 protein (Endod1), which functions as a tumor suppressor, particularly in prostate cancer, and is implicated in innate immune responses." (PMID 41342963, 2025). "ENDOD1 was also reported as a candidate tumor suppressor and inhibits proliferation, migration, and invasion in prostate cancer." (PMID 39594630, 2024). "ENDOD1 exhibited a stepwise down-regulation during disease progression (P<0.05 for Post linear-trend test), which is consistent with the results from the prostate cancer databases." (PMID 21829708, 2011). "Our results indicate that ENDOD1 is a novel tumor suppressor in PCa, which may be employed as a new drug target of preventing progression to metastatic castration-resistant prostate cancer." (PMID 28532481, 2017). "In this study, we aimed to investigate the role of ENDOD1 in prostate cancer (PCa)." (PMID 28532481, 2017). "We selected three R1881-regulated genes to be analyzed by quantitative PCR on normal prostate and prostate carcinoma samples obtained in our institute: ACSL3, MCCC2 and ENDOD1." (PMID 21829708, 2011). "In order to identify androgen-regulated genes that could possibly be used in the diagnosis/prognosis of prostate cancer, we selected from our 107-gene signature three androgen-regulated genes: MCCC2, ENDOD1 and ACSL3." (PMID 21829708, 2011).
melanoma (2 papers, 2008 to 2019). A malignant, usually aggressive tumor composed of atypical, neoplastic melanocytes. "Similarly, the up-regulated genes in the ABCB5 CTC fractions were involved in metastasis (CALU, CYB5R1, DUSP3, CREG1, ENDOD1), tumour growth, and/or melanoma biology (H1F0, SCNA, WIPI1, TXN2)." (PMID 30769764, 2019). "The Met library genes were not able to distinguish between primary and metastatic melanomas, since only one gene, ENDOD1 that codes for a putative endonuclease, was detected by SAM, at FDR = 0, as differentially expressed between the two tumor stages." (PMID 18211678, 2008).
prostate tumor (2 papers, 2011 to 2020). "Data on ACSL3, MCCC2 and ENDOD1 protein expression is available for 3 normal tissue samples and 11 prostate tumors." (PMID 21829708, 2011).
Cerebral ischemia (1 paper, 2025). Restriction of arterial blood supply to the brain associated with insufficient oxygenation to support the metabolic requirements of the tissue. "Although ENDOD1 has not been directly associated with stroke or ischemia, the established involvement of other endonuclease-related proteins (e.g., endonuclease VIII-like 1 and endonuclease G) in ischemic injury suggests a potential, yet unexplored, relevance in cerebral ischemia." (PMID 41342963, 2025).
colorectal cancer (1 paper, 2017). A primary or metastatic malignant neoplasm that affects the colon or rectum. "Similarly, downregulation of ENDOD1 was revealed in colorectal cancer compared to the normal mucosa and proposed to be involved in epithelial tumorigenesis." (PMID 28532481, 2017).
soft tissue tumors (1 paper, 2017). "In soft tissue tumors, decreased ENDOD1 correlated with local aggressiveness." (PMID 28532481, 2017).
tumor (11 papers, 2008 to 2025). "Therefore, there’s probability that ENDOD1 functions as tumor suppressor through preventing aberrant alteration of mutation, DNA repair and programmed cell death." (PMID 28532481, 2017). "For further investigation on the impact of ENDOD1 in tumor biology of PCa, we selected LNCaP and DU145 cells as study models." (PMID 28532481, 2017). "Nevertheless, our study identified ENDOD1 is a novel tumor suppressor, which may add our knowledge about PCa progression." (PMID 28532481, 2017). "Since AR plays critical role in promoting PCa tumor growth and progression, ENDOD1 is likely to be the mediator of AR signaling in the progression to mCRPC and could possibly be used as markers in predicting the course of disease." (PMID 28532481, 2017). "We previously already identified Endod1 and Susd2 as tumor suppressor genes and as downstream targets of the NOTCH pathway, which harbors potent tumor suppressive capabilities in the skin and oral cavity." (PMID 36765696, 2023).
cancer (1 paper, 2022). A tumor composed of atypical neoplastic, often pleomorphic cells that invade other tissues. "Combined with xenograft data the work identifies ENDOD1 as a potential cancer-specific SL drug discovery target." (PMID 35606358, 2022). "In summary, we identify ENDOD1 as a potential wide-spectrum and cancer-specific target for SL drug discovery." (PMID 35606358, 2022). "This suggests that targeting ENDOD1 in HRD cancers may provide an alternative to PARPi therapy." (PMID 35606358, 2022). "In contrast, a range of HR-competent non-cancer cells (including RPE1 and GES-1) exhibited no proliferation defects upon siRNA ablation of ENDOD1." (PMID 35606358, 2022).
ENDOD1 also shares sentences with these, for which no sentence is quoted: breast carcinoma (1 paper); colon cancer (1); endometriosis (1); infection (1); ischemia (1); lymph node metastasis (1); pancreatic ductal adenocarcinoma (1); Stroke (1).